MMP8 (matrix metallopeptidase 8)
Diseases named in the same sentence as MMP8 in open-access papers (continued):
Sharing a sentence is not in itself a finding about the gene and the disease.
chronic lung disease (1 paper, 2025). According to the definitions of the American and British Thoracic Societies, including pulmonary functional tests, X-rays, and CT scans for items such as fibrosis, bronchiectasis, bullae, emphysema, nodular or lymphomatous abnormalities. "MMP8 contributes to tissue remodeling in chronic lung diseases, while S100A9, a calcium-binding protein, amplifies neutrophilic inflammation." (PMID 41044788, 2025).
clear cell renal carcinoma (1 paper, 2024). A malignant epithelial neoplasm of the kidney characterized by the presence of lipid-containing clear cells within a vascular network. "The matrixdegradation by invasive clear cell renal carcinoma cells is supportedby significant upregulation of genes, including MMP7 and MMP8, and downregulation of the key basement membraneprotein collagen IV (COL4) gene." (PMID 39398183, 2024).
co-infection (1 paper, 2020). "Elevated sputum and plasma levels of MMP-8 are present in TB individuals, TB- immune reconstitution inflammatory syndrome (IRIS) and in individuals with and without HIV co-infection." (PMID 32218787, 2020).
cognitive decline (1 paper, 2025). "Patients involved in immunovascular signaling (MMP8), synaptic vesicle fusion (SNAP23) and lipid trafficking (APOB) pathways relevant to APOE biology and cognitive decline." (PMID 40665048, 2025).
colibacillosis (1 paper, 2025). "The MMP8 gene, encoding matrix metalloprotease 8 (MMP-8), showed elevated expression in piglets receiving ineffective treatment for colibacillosis." (PMID 40995220, 2025).
cutaneous melanoma (1 paper, 2019). A primary melanoma arising from atypical melanocytes in the skin. "High serum MMP8 levels could be used to define cutaneous melanoma patients who would benefit from interferon-α (IFN-α) therapy." (PMID 31514474, 2019).
cystic fibrosis (1 paper, 2023). Autosomal recessive disorder caused by pathogenic variants in the CFTR gene (cystic fibrosis transmembrane conductance regulator), which encodes a chloride and bicarbonate channel expressed in epithelial cells, and follow the diagnosis criteria. "Notably, using a quantitative proteomic and bioinformatic approach, we identified several metalloprotease proteins usually involved in cystic fibrosis, such as matrix metalloproteinase 8 (MMP8), MMP9, and matrix metalloproteinase 16 (MMP16)." (PMID 37686190, 2023).
dementia (1 paper, 2025). Loss of intellectual abilities interfering with an individual's social and occupational functions. "Similarly, proteins such as MMP8, IL32, NDRG1, SMOC2, or ESM1, which have been previously reported to contribute to AD pathology, showed to be significantly increased in both MCI A + T + and AD dementia, but not in MCI A-T-, suggesting a specific AD-related signature in pEVs proteome." (PMID 41282153, 2025).
diabetic nephropathy (1 paper, 2021). "MMP8 and its various molecular subtypes have been found in the urine of diabetic nephropathy patients, and MMP8 reportedly plays an important role in the pathogenesis of diabetic nephropathy." (PMID 34211440, 2021).
dry eye (1 paper, 2024). "A study comparing the tear fluid from pSS patients with that of non-SS dry eye subjects revealed upregulated protein metabolism involving MMP8, SERPINB5, RPLP2, CSTB, and CST3 in pSS patients compared to controls." (PMID 39408709, 2024).
dysplasia (1 paper, 2008). A usually neoplastic transformation of the cell, associated with altered architectural tissue patterns. "The estimated proportion of female MMP-8 KO mice developing either dysplasia or carcinoma was 67 percent points higher than that of the female wild-type mice (83 vs 17%; 95% CI for the difference in proportions: +21 to +85 percent points)." (PMID 18253113, 2008).
endocarditis (1 paper, 2021). Inflammation of the endocardium. "Interestingly, higher MMP-8 and TIMP-1 levels were associated to presence of a deep infection focus but not to endocarditis." (PMID 34043679, 2021).
Endotoxemia (1 paper, 2012). "We hypothesized that MMP-8 plays also a role in the lung response to endotoxemia." (PMID 22768176, 2012). "Herein, we report the results of a model of endotoxemia after intraperitoneal LPS injection in mice lacking MMP-8 and their wildtype counterparts." (PMID 22768176, 2012).
enteritis (1 paper, 2018). Inflammation of the small intestine. "Furthermore, in much older reports, MMPs, MMP-8 in particular, have been shown to be important in reactive arthritis, a frequent sequela of bacterial enteritis including that caused by Campylobacter." (PMID 30551610, 2018). "As the MMP-8/TIMP-1 and MMP-9/TIMP-1 ratios were concerned in enteritis patients, significant differences between acute and convalescent samples were detected except for MMP-9/TIMP-1 ratio for Salmonella patients." (PMID 30551610, 2018).
epilepsy (1 paper, 2014). A brain disorder characterized by episodes of abnormally increased neuronal discharge resulting in transient episodes of sensory or motor neurological dysfunction, or psychic dysfunction. "The minimum p value of association with outcome of newly treated epilepsy for any susceptibility locus was 8·14 × 10−4 (MMP8)." (PMID 25087078, 2014).
falciparum malaria (1 paper, 2025). "Multiple studies implicate the MMP pathway: serum TIMP-1 and MMP-8 are elevated in falciparum malaria and TIMP-1 correlates with severity, and in pediatric CM retinal MMP-8 locally co-localizes with fibrinogen leak at sites of sequestration, consistent with endothelial barrier disruption." (PMID 41002937, 2025).
gastric varices (1 paper, 2010). "Furthermore, these findings were accompanied by a clear improvement in collateral circulation and gastric varices, suggesting diminished intrahepatic blood pressure in animals injected with Ad-huPA plus Ad-MMP-8 (data no show)." (PMID 20509929, 2010).
gastrointestinal mucositis (1 paper, 2022). "Our study has demonstrated that gastrointestinal mucositis induced by 5-FU increases the activity of the proteolytic enzymes MMP-1, MMP-2, MMP-8, and TIMP-1 in sera and tissues." (PMID 36290656, 2022).
gingival hemorrhage (1 paper, 2025). "The gingival hemorrhage index is positively correlated with MMP-8, which is synthesized by polymorphonuclear leukocytes." (PMID 41466021, 2025).
gonococcal infection (1 paper, 2017). "ELISA results supported these findings and showed that MMP-8 release increased upon gonococcal infection." (PMID 28932707, 2017).
granulocytic leukemia (1 paper, 2022). "Matrix metalloproteinase-8 (MMP-8), collagenase-2, or neutrophil collagenase, identified in 1968 in human neutrophils and gingiva, were cloned from neutrophils from a granulocytic leukemia patient." (PMID 35757444, 2022).
hematoma (1 paper, 2022). A hematoma is a collection of blood from a vascular structure into an extravascular space. "Future studies should analyze the associations between MMP-8 concentration in preoperative/postoperative serum and hematoma fluid to elucidate its role in CSDH formation." (PMID 35207175, 2022). "In our study, we observed that the concentration of MMP-8 was higher in hematoma fluid than in the preoperative peripheral blood, decreasing following treatment." (PMID 35207175, 2022). "Our analysis indicated that VEGF, PDGF-BB, TNF-alpha, MMP-9, IL-6, CCL2, IL-1 alpha, MMP-1, MMP-8, and IL-8 were DEGs between the hematoma fluid and the peripheral blood before surgery." (PMID 35207175, 2022).
Hepatic steatosis (1 paper, 2025). Steatosis is a term used to denote lipid accumulation within hepatocytes. "Mechanistically, MCT4 alleviated hepatic steatosis by regulating a group of hub genes such as Arg2, Olr1, Cd74, Mmp8, Irf7, Spp1, and Apoe, which in turn impacted multiple pathways involved in lipid metabolism and inflammatory response, such as PPAR, HIF-1, TNF, IL-17, PI3K-AKT, Wnt, and JAK-STAT." (PMID 40330148, 2025).
hepatoblastoma (1 paper, 2011). Hepatoblastoma (HB) is a malignant hepatic tumor and is the most common pediatric liver cancer. "The result suggests that recombinant MMP-8, not induced by irradiation, will not influence the PKs of 5-FU in liver cells and has no significant toxicity to human hepatoblastoma-derived cell line, HepG2." (PMID 21695264, 2011).
Hypoalbuminemia (1 paper, 2020). The concentration of albumin in the blood circulation is below the lower limit of normal. "The administration of albumin and a high-casein diet also increased the tissue expression of EGFR, ERK1, ERK2, TGF-β, and collagen and decreased that of MMP-8 relative to the hypoalbuminemia control (P < 0.05)." (PMID 32518615, 2020). "We also detected upregulated expression of MMP-8 and delayed wound repair in the hypoalbuminemia group." (PMID 32518615, 2020). "In contrast, MMP-8 expression had decreased significantly by postoperative day 5 compared with the hypoalbuminemia group." (PMID 32518615, 2020). "However, after pre- and postsurgical albumin infusion or administration of a normal protein diet, the levels of TNF-α, IL-1, IL-6, CRP, and MMP-8 were significantly reduced relative to the hypoalbuminemia group." (PMID 32518615, 2020). "Hotelling's t analysis revealed significant differences among the presurgical albumin infusion (B), presurgical normal protein diet (C), and hypoalbuminemia (D and E) diet groups in terms of serum levels of albumin, TNF-α, IL-1, IL-6, CRP, and MMP-8 (P=0.01)." (PMID 32518615, 2020).
infarction (1 paper, 2024). A localised pathological necrosis of tissue resulting from obstruction of the blood supply usually by a thrombus, an embolus, or vascular torsion. "Thus, the estimation of MPO and MMP-8 elucidates not only the pathogenetic importance of NETosis but also provides notable contributions to the diagnosis of NSTEMI and the risk of necrotic zone expansion in the post-infarction evolution of the patient." (PMID 39351477, 2024).
inflammatory breast carcinoma (1 paper, 2008). An advanced, invasive breast adenocarcinoma characterized by the presence of distinct changes in the overlying skin. "The median plasma MMP1 (p = 0.02) and MMP8 (p = 0.007) levels in the non-inflammatory breast cancer patients were almost twice as high as those found in the inflammatory breast cancer patients." (PMID 18366705, 2008). "Likewise, the median value of plasma MMP8 levels in the population of non-inflammatory breast cancer patients was almost twice as high as those found in the inflammatory breast cancer group (OR 0.90, p < 0.01)." (PMID 18366705, 2008).
keratoacanthoma (1 paper, 2019). A dome-shaped, rapidly growing skin lesion composed of well differentiated squamous cells. "However, MMP8 was slightly more frequently detected in neutrophils in keratoacanthomas (~44%) compared to SCCs (~33%)." (PMID 31514474, 2019).
larynx tumors (1 paper, 2019). "MMP8 protein did not have a prognostic value in larynx tumors where its levels varied greatly between patients, nor in supraglottic laryngeal tumors where it was detected in only a few cells." (PMID 31514474, 2019).
Lassa fever (1 paper, 2021). A viral hemorrhagic fever that is caused by the Lassa virus, which is transmitted by contact with infected rodents; it is characterized by fever, headache, malaise, myalgia, and hearing loss. "Genes involved in extracellular matrix and cell-adhesion were also modulated, particularly during fatal Lassa fever (NID1, TIMP3, ITGA11, TGM2, MMP8/9, OLFM4, PCDH20, and CADM3), as well as some others involved in coagulation (SERPIN, TFPI2) and apoptosis (CLU, BCL2L14)." (PMID 33398113, 2021).
liver disease (1 paper, 2014). "MMP-8, MMP-9, YKL-40, and TIMP-1 serum levels were unaffected by the presence or absence of CF liver disease or pancreatic insufficiency." (PMID 25545245, 2014).
mastitis (1 paper, 2025). Inflammation of breast tissue during lactation or postpartum due to an obstructed duct or infection. "Similarly, MMP8 expression has been reported to be higher in cows with clinical mastitis than in cows with subclinical mastitis or healthy cows." (PMID 41252605, 2025).
meningioma (1 paper, 2024). A generally slow growing tumor attached to the dura mater. "In meningiomas, the protein levels of MMP1, MMP2, and MMP3 were similar to controls, but a slight decrease in MMP8 protein levels was identified." (PMID 38474106, 2024).
myopia (1 paper, 2012). "Initial findings indicated that the best p values for each trait were 0.02 for myopia at rs2274755 (MMP9), 0.02 for SE at both rs3740938 (MMP8) and rs131451 (MMP11), 0.01 for axial length at rs11225395 (MMP8), 0.01 for anterior chamber depth at rs498186 (MMP1) and 0.02 at rs10488 (MMP1)." (PMID 23077567, 2012).
Neurodegeneration (1 paper, 2021). Progressive loss of neural cells and tissue. "Due to the fact that T2D and neurodegeneration disease shared the overlapping pathophysiological mechanisms and pathways, we detected Mmp8 and Hif3α mRNA expression value in AD and PD samples by analyzing gene expression datasets in GEO." (PMID 34975464, 2021).
non-small cell lung carcinoma (1 paper, 2021). A group of at least three distinct histological types of lung cancer, including non-small cell squamous cell carcinoma, adenocarcinoma, and large cell carcinoma. "In this study, we aimed to investigate the role of MMP8 in non-small cell lung cancer proliferation and invasiveness potential." (PMID 34356991, 2021).
osteomyelitis (1 paper, 2025). An acute or chronic inflammation of the bone and its structures due to infection with pyogenic bacteria. "We next investigated the clinical significance of PCD pathways by correlating their GSVA scores with representative inflammatory biomarkers of osteomyelitis, including IL6R, MMP8, TNFRSF11A, IL17RB, TNFSF14, and TGFBR1." (PMID 41050653, 2025).
ovarian tumor (1 paper, 2010). "Indeed, MMP-8 expression significantly correlated with ovarian tumor grade, tumor stage, and poor prognosis." (PMID 20649989, 2010).
papilloma (1 paper, 2010). A benign epithelial neoplasm that projects above the surrounding epithelial surface and consists of villous or arborescent outgrowths of fibrovascular stroma. "Another collagenase, MMP8 when silenced resulted in decreased latency period and increased number of papillomas." (PMID 21170377, 2010).
Parkinson disease (1 paper, 2024). A progressive degenerative disorder of the central nervous system characterized by loss of dopamine producing neurons in the substantia nigra and the presence of Lewy bodies in the substantia nigra and locus coeruleus. "MMP8 inhibitors can also mitigate neuroinflammation in a Parkinson’s disease model with LRRK2 G2019S mutation." (PMID 38419037, 2024). "Previous studies have shown that MMP8 inhibition can decrease the production of reactive oxygen species (ROS) and expression of inflammatory genes in conditions such as Parkinson’s disease and cerebral ischemia, thereby reducing neuroinflammation." (PMID 38419037, 2024).
pneumococcal infection (1 paper, 2018). Infections with bacteria of the species streptococcus pneumoniae. "When we analyzed the expression of these and other MMPs, we observed that the pneumococcal infection indeed induced the expression of MMP‐2, MMP‐3, MMP‐8 and pro‐MMP9 in the respiratory tract of AIRmax mice." (PMID 29119707, 2018).
pterygium (1 paper, 2021). A wedge-shaped fibrovascular lesion arising from the bulbar conjunctiva and extending to the cornea. "In this study, multiple types of MMPs (MMP2, MMP3, MMP8, MMP9, MMP11, MMP16, and MMP28) were highly expressed in pterygium." (PMID 33790949, 2021).
pulmonary sarcoidosis (1 paper, 2021). Sarcoidosis affecting the lung parenchyma. "The increase in MMP-8 level in BALF leads to collagenase activity in patients with pulmonary sarcoidosis; therefore, we speculate that neutrophils might exert similar profibrotic effects in pulmonary sarcoidosis." (PMID 35186971, 2021).
pyelonephritis (1 paper, 2019). An inflammatory process affecting the kidney. "The obtained results for MMP-8 are associated with the formation of two subgroups among the examined children suffering from pyelonephritis, based on their mRNA levels." (PMID 31881666, 2019). "Further investigations with definite tendency of increase of the number of participants suffering from the common health disorder of pyelonephritis will contribute to proper evaluation of mRNA levels of IL-6, MMP-8 and GSS as salivary biomarkers." (PMID 31881666, 2019). "Salivary IL-6, MMP-8 and GSS mRNA levels in combination with urine test analysis could be useful diagnostic tool for the very distributed disorder of pyelonephritis in childhood." (PMID 31881666, 2019). "Salivary IL-6, MMP-8 and GSS mRNA levels in combination with urine test analysis could be a useful diagnostic tool for the very distributed disorder of pyelonephritis in childhood." (PMID 31881666, 2019). "MMP-8 and GSS mRNA levels were increased in 12 samples in patients with pyelonephritis 3.27 (p < 0.01) and 1.94 (p < 0.001) times, respectively." (PMID 31881666, 2019). "We recorded that the mRNA levels of the pro-inflammatory cytokine IL-6 were considerably higher compared to these of MMP-8 and GSS for all 28 children with pyelonephritis." (PMID 31881666, 2019). "Analysis of the mRNA levels for IL-6, MMP-8 and GSS in 28 children hospitalized with the diagnosis of pyelonephritis was conducted applying the method of quantitative reverse transcription polymerase chain reaction (RT-qPCR)." (PMID 31881666, 2019). "Among all 28 participants with diagnosed pyelonephritis, nine showed considerably high mRNA levels of IL-6, MMP-8 and GSS (Patients No 1, 12, 16, 17, 19, 21, 23, 24, 28)." (PMID 31881666, 2019).
renal fibrosis (1 paper, 2020). A final common manifestation of a wide variety of chronic kidney diseases characterized by glomerulosclerosis and tubulointerstitial fibrosis. "The results showed that AdhMMP8 decreased renal fibrosis, suggesting that MMP8 could be a possible therapeutic candidate for kidney fibrosis treatment." (PMID 33275619, 2020).
respiratory infections (1 paper, 2022). "The specificity of high plasma MMP-8 concentrations, especially in the context of other respiratory infections, requires further study." (PMID 35510939, 2022).
retinopathy of prematurity (1 paper, 2017). A bilateral retinopathy characterized by neovascularization, scarring, retinal detachment, and eventually blindness. "Levels of THBS1, MMP8, MMP9, MMP25, TIMP2 and TIMP3 increased as severity of BPD and retinopathy of prematurity (ROP) increased, whereas ETS1, LEF1 and SPOCK2 exhibited the opposite trend." (PMID 28103583, 2017).
rheumatic disease (1 paper, 2021). "However, within the limits of this study, the effect of rheumatic disease on the salivary MMP‐8 level could not be adequately studied and more extensive studies are needed to confirm the previous results." (PMID 34448550, 2021).
sarcoidosis (1 paper, 2014). Sarcoidosis is a multisystemic disorder of unknown cause characterized by the formation of immune granulomas in involved organs. "We used publicly-available microarray gene expression databases to compare MMP-8 expression in peripheral blood mononuclear cells (PBMCs) from COPD versus healthy control subjects and sarcoidosis patients versus healthy control subjects." (PMID 24828408, 2014). "Our analysis shows that MMP-8 transcripts are not detected in COPD PBMCs and MMP-8 expression is not significantly increased in PBMCs from patients with sarcoidosis." (PMID 24828408, 2014).
septic arthritis (1 paper, 2024). "Of these, neutrophil collagenase (MMP8) was most consistent with a fold change of 22.9 when comparing septic arthritis before (PID1) and post eradication of joint infection (PID4), and a 4.2 fold change when comparing septic arthritis and experimentally induced non-septic synovitis PID1." (PMID 39057983, 2024).